EIF2A (eukaryotic translation initiation factor 2A)
Diseases named in the same sentence as EIF2A in open-access papers (continued):
Sharing a sentence is not in itself a finding about the gene and the disease.
Leukoencephalopathy (1 paper, 2011). This term describes abnormality of the white matter of the cerebrum resulting from damage to the myelin sheaths of nerve cells. "Mutations in each of the five subunits of the translation initiation factor eIF2B, including eIF2a encoded by EIF2B1 [Ensembl:ENSCAFG00000007434], can cause leukoencephalopathy with vanishing white matter (VWM, [OMIM:603896])." (PMID 21722374, 2011).
lymph node metastasis (1 paper, 2016). "By univariate analysis, higher pathologic tumor (pT) stage, presence of lymph node metastasis, higher pTNM stage, chemotherapy regimen with both AC and taxane, lower level of TILs, and lower expression of p-eIF2a were negative prognostic factors for both disease-free and overall survival." (PMID 27494867, 2016).
lymphoma (1 paper, 2022). A malignant (clonal) proliferation of B- lymphocytes or T- lymphocytes which involves the lymph nodes, bone marrow and/or extranodal sites. "Finally, although ATF4 protein showed positive correlation with the relative abundance of phospho-EIF2A (p-EIF2A/EIF2A), the phospho-EIF2A levels only showed the trend of decrease in Sirt3−/− versus Sirt3WT lymphomas cells but was not statistically significant." (PMID 35019856, 2022).
memory impairment (1 paper, 2015). "This is highlighted by recent work in which the conditional knockout of eIF2a kinases (PERK and GCN2) prevented Aβ induced impairment in long term potentiation (LTP) (synaptic activity) and memory impairment in AD transgenic mice." (PMID 26693205, 2015).
ovarian carcinoma (1 paper, 2020). A malignant neoplasm originating from the surface ovarian epithelium. "Additionally, we confirmed that the cascades of the ER stress sensor-growth arrest- and DNA damage-inducible gene 153 (GADD153) and phosphorylated eukaryotic translation-initiation factor 2a (p-eIF2a) increased in fucoidan-treated ovarian cancer cells." (PMID 31936539, 2020).
pancreatic cancer (1 paper, 2023). "Therefore, targeting the PERK/eIF2a/ATF4 pathway can be used to inhibit EMT in pancreatic cancer cells." (PMID 37790807, 2023). "Gene enrichment analysis showed that by blocking eIF2a phosphorylation and reducing ATF4 translation, acriflavine inhibited the unfolded protein-responsive PERK/eIF2a/ATF4 pathway, that is, acriflavine restored the drug sensitivity of acquired drug-resistant pancreatic cancer cell lines." (PMID 37790807, 2023).
Primary hypothyroidism (1 paper, 2019). A type of hypothyroidism that results from a defect in the thyroid gland. "The possible underlying mechanism of primary hypothyroidism might be that a deficiency in EIF2A decreases type 2 deiodinase synthesis during ER stress, leading to reduced intracellular thyroid hormone activation." (PMID 30922274, 2019).
prostate carcinoma (1 paper, 2024). A carcinoma that arises from epithelial cells of the prostate gland. "ROS in prostate cancer could also induce endoplasmic reticulum (ER) stress mediated through upregulation of p-eIF2α (eukaryotic translation initiation factor 2A) and ATF4." (PMID 39376605, 2024).
Sepsis (1 paper, 2020). Sepsis is defined as life-threatening organ dysfunction caused by a dysregulated host response to infection. "In a gram-negative animal sepsis model, the EIF1/EIF2a transcription regulators were mediators of translation initiation block in late-phase sepsis when transcriptomic changes were examined at multiple time points." (PMID 32154187, 2020).
steatosis (1 paper, 2015). Increased lipid within the cytoplasm of cells. "Furthermore, Tpl2 ablation resulted in decreased hepatic steatosis and expression of de novo lipogenesis related markers (ACC, SCD1, SREBP1C and AKT phosphorylation), as well as reduction of endoplasmic reticulum stress biomarkers PERK and eIF-2a." (PMID 26560698, 2015).
tauopathy (1 paper, 2017). Neurodegenerative disorders involving deposition of abnormal tau protein isoforms (tau proteins) in neurons and glial cells in the brain. "The rationale behind PERK inhibition was that chronic overactivation of PERK in tauopathies may lead to a disadvantageous long‐term suppression of translation by phosphorylation of EIF2A." (PMID 28148553, 2017). "We therefore investigated the state of PERK, EIF2A, and NRF2 in postmortem human PSP brains and the effects and mechanisms of PERK activation and inhibition in models of tauopathies." (PMID 28148553, 2017). "Importantly, the PERK substrate EIF2A, mediating some detrimental effects of PERK signaling, was downregulated in PSP brains and tauopathy models, suggesting that the alternative PERK–NRF2 pathway accounts for these beneficial effects in the context of tauopathies." (PMID 28148553, 2017).
cancer (30 papers, 2012 to 2025). A tumor composed of atypical neoplastic, often pleomorphic cells that invade other tissues. "Their elevated expression is associated with decreased promoter methylation at cancer stages 2, 3, and 4, as well as copy number amplifications in EIF2A and EIF2B5 genes." (PMID 38001610, 2023). "Elegant studies have recently implicated eIF2A in cancer progression because it is involved in the initiation of translation of upstream ORFs." (PMID 29487587, 2018). "Additionally, angiogenesis and metastasis in cancer cells are linked to the PERK/eIF2a signaling pathway." (PMID 37143570, 2023). "Context-dependent translation regulation plays a major role in cancer progression, and several observations link eIF2A to cancer." (PMID 40749049, 2025). "The apoptotic phenotype observed in vivo and in vitro under Macrocarpal I treatment further experimentally validated that Macrocarpal I promotes cancer cell apoptosis through activating the PERK/eIF2a/ATF4/CHOP signaling pathway." (PMID 39987121, 2025). "Ribosome biogenesis, for example, is a process frequently altered in cancer and also a prominent functional term of the eIF2A interactome." (PMID 40749049, 2025). "Nevertheless, it will be important for the field to determine if concentrating eIF2A to organelles and away from the translation machinery provides a competitive advantage or increased fitness for cancer cells." (PMID 37602404, 2023). "Recent research revealed that when exposed to diverse microenvironmental stimuli during tumorigenesis, cancer cells suffered reduced canonical translation and switched their translational machinery to EIF2A-dependent translation." (PMID 37064149, 2023). "PKR is a kinase whose activity is enhanced in cancer cells, and phosphorylation of eIF2a occurring downstream of PKR signaling negatively regulates transcription and protein synthesis." (PMID 36476676, 2022). "Our work highlights the importance of investigating the interplay between different proteostatic pathways and supports ongoing efforts to modulate GCN2 and eIF2a phosphorylation in cancer." (PMID 34180400, 2021). "The authors showed that the loss of ISR increases paclitaxel-mediated cell death and that eIF2A is one of the key and essential factors for cancer cell survival under the conditions of paclitaxel-mediated ISR." (PMID 32192132, 2020). "Several additional recent reports have shown that eIF2A has specific functions during the ISR as well as cancer progression." (PMID 32192132, 2020). "We demonstrated that the alternative initiation factor EIF2A was essential for cancer cell survival after paclitaxel‐mediated ISR both in vitro and in vivo." (PMID 31211507, 2019). "Nonetheless, eIF2A is likely required for additional functions besides its involvement in cancer progression." (PMID 29487587, 2018). "At the molecular level, FK866-resistant cancer cells were found to effectively prevent the activation of the EIF2A/ATF4/CHOP pathway that promotes cell death." (PMID 29541451, 2018). "Together these observations clearly indicate the critical involvement of EIF2AK3/PERK in the phosphorylation of EIF2A, cyclin D loss and the attenuation of pRB phosphorylation seen in CCT020312-treated cancer cells." (PMID 22253692, 2012). "Studying the role of eIF2A in the migration of other cancer types could reveal broader implications for targeting eIF2A therapeutically." (PMID 40749049, 2025). "In 2014, Yuxin Yin and co-authors found that eIF2A controls the expression of one of the isoforms of the phosphatase and tensin homologue deleted on chromosome 10 (PTEN) protein (which is lost or mutated in many cancers)." (PMID 32192132, 2020). "Knockdown of eIF2A substantially impaired cancer cell survival under the ISR." (PMID 32192132, 2020). "Importantly, in both cell models, cancer cell death appeared to occur via reactivation of the EIF2A/ATF4/CHOP pathway." (PMID 29541451, 2018).
cancer (continued). "Interestingly, cancer cells were also shown to modify their response to eIF2 phosphorylation by expression of the alternative translation initiation factor eIF2A." (PMID 29634759, 2018). "IR induced ERSR signaling in cancer is supported by IR induction of the PERK/eIF2a pathway." (PMID 26716508, 2016). "Moreover, phosphorylation of eIF2a, an event that negatively regulate tertiary complex formation, was deregulated in cancer, although the exact function of eIF2a phosphorylation in cancer biology is controversial and may be context-dependent." (PMID 36187485, 2022). "This included ERα, the transcriptional repressor protein E2F-4, the microtubule protein αTubulin and proteins involved in cancer cell metabolism (GLUT1, LDHA and PDK1-pSer241) and stress responses (eIF2A-pSer51)." (PMID 37596623, 2023). "The pathways in cancer and Thyroid hormone synthesis signaling pathway and the first two genes of CXCL12 and EIF2A are considered to be biomarkers of important biological function in IS." (PMID 33880887, 2021). "Therefore, understanding the effects of eIF2A on selective protein synthesis and its role in disease development (such as, e.g., cancer) is extremely important, as it may further provide an experimental platform to aid in the design and discovery of novel therapeutics." (PMID 32192132, 2020). "Uncharacteristic of translation initiation factors, eIF2A is reported to be non-cytosolic in multiple human cancer cell lines." (PMID 37602404, 2023). "In cancer cells, ACF has been shown to inhibit the unfolded protein response (UPR) pathway via inhibition of eukaryotic translation initiation factor 2A (eiF2a) phosphorylation and downregulation of the activating transcription factor 4 (ATF4) transcriptional program." (PMID 36227697, 2022). "In conclusion, our study confirmed that pathways in cancer and gyroid hormone synthesis signaling pathway and two hub genes related to IS (CXCL12 and EIF2a) may be potential biomarker for accurate diagnosis and treatment of IS in future." (PMID 33880887, 2021). "More recently, in the absence of cancer, chemotherapeutic agents such as doxorubicin have been shown to reduce skeletal muscle protein synthesis rates independent of key mTORC1 and eIF2a regulatory signaling." (PMID 33348673, 2020). "Mechanistically, BOLD-100 has been shown to down-regulate GRP78 in thapsigargin-mediated stressed cancer cells and trigger immunogenic cell death through the PERK/EIF2a branch of the UPR accompanied by ROS production, release of high mobility group box 1 (HMGB1) and ATP secretion via autophagy." (PMID 32947941, 2020). "In addition, adding EIF2A protein to the HS-766T cells significantly induced the elevation of ID1 in HS-766T cells, further validating that ID1 gene was regulated by EIF2 signaling in PDAC cancer cells." (PMID 35941362, 2022). "Interestingly, in our cell model and at the doses we used, we did not observe Compound C-induced phosphorylation of EIF2A as recently reported in different cancer cells." (PMID 26542945, 2015). "In addition, eIF2A promotes translation from an upstream CUG in PTEN mRNA, leading to an N-terminally extended form of PTEN called PTENα that participates in mitochondrial energy metabolism and supports the energetic demand of rapidly proliferating cancer cells." (PMID 40749049, 2025).
tumor (30 papers, 2014 to 2025). "Anthracycline-induced phosphorylation of eukaryotic translation initiation factor 2A (eIF2α) causes exposure of calreticulin in tumor cells, which acts as an “eat me” signal; thus, DCs phagocytose calreticulin-exposed tumor cells." (PMID 35806328, 2022). "eIF2A has also been implicated in stimulating translation of positive-acting uORFs initiated by CUG or other NCCs during tumor initiation in a manner important for tumor formation in animals." (PMID 38266075, 2024). "It has been implicated as a tumor suppressor because of its ability to phosphorylate eIF-2a." (PMID 27106056, 2016). "The RNA-binding protein eukaryotic translation initiation factor 2A (eIF2A) is an alternative translation initiation factor shown to drive tumor formation by facilitating translation from near-cognate initiation codons." (PMID 40749049, 2025). "Overall, these findings suggested that PERK-mediated eIF2a phosphorylation is responsible for the enhanced anti-tumor effect of C + D treatment." (PMID 39090653, 2024). "Consistently, the scRNA-seq analysis revealed that the expression levels of Perk, Eif2a, Chop, and Casp12 were significantly upregulated in the T1 tumor cluster from Ero1aKO tumors compared with WT counterparts, suggesting they were more susceptible to death." (PMID 37769655, 2023). "All these data suggested a core regulation potential of EIF2A in tumor formation gene expression patterns and tumorigenesis of PDAC." (PMID 35941362, 2022). "Tumor cell apoptosis is facilitated by eIF2a-CHOP-BcL-2/JNK and IRE1a-XBP1/JNK signaling and by microRNAs." (PMID 35327364, 2022). "The authors thus concluded that eIF2A-mediated translation is important for tumor initiation and progression." (PMID 32192132, 2020). "Immunohistochemical staining showed that the tumours treated with doxycycline exhibited lower expression of EIF2A and stronger phosphorylated EIF2S1 than that in the controls." (PMID 31211507, 2019). "A recent study reveals that EIF2A is essential for tumourigenesis and progression, because tumours exhibit more ISR than normal tissue in tumourigenesis, during which EIF2A maintains efficient translation of many genes related to tumourigenesis." (PMID 31211507, 2019). "Tumour growth was associated with decreases in mTOR and p70S6K1 gene expression, as well as reduced expression of eIF4E, eIF5 and eIF2a, three factors involved in protein synthesis (the tumour effect was highly significant at P < 0.05)." (PMID 26847205, 2016). "The presence of calreticulin on the tumor-cell surface requires PERK-mediated phosphorylation of the translation initiation factor eIF2a." (PMID 24480782, 2014). "Last, although we focus on centrosome interactions in this work, there are other interactions of eIF2A identified in this study that could contribute to tumor progression." (PMID 40749049, 2025). "Furthermore, we injected ISRIB into mice to inhibit the C + D-induced eIF2a phosphorylation and evaluated the anti-tumor effect of C + D treatment on established CT26 subcutaneous tumors." (PMID 39090653, 2024). "Utilizing ribosome sequencing alongside an RNA interference-based screen, they observed that global mRNA translation was surprisingly lower than in normal cells due to ISR signaling for selective translation through uORFs requiring eIF2A for tumor initiation and progression." (PMID 37601686, 2023). "More recently, Jonathan Weissman, Elaine Fuchs and their colleagues showed that eIF2A may be involved in tumor initiation and progression." (PMID 32192132, 2020). "Our present study demonstrated that Tpl2 ablation decreased ER stress mediated PERK expression and eIF-2a activation, which might account for the decreased tumor incidence." (PMID 26560698, 2015). "Thus the effect of the tumor PERK/P/EIF2A signaling pathway is controversial." (PMID 36593497, 2023).
tumor (continued). "Our study also highlights the importance of the PERK-mediated eIF2a phosphorylation-induced CALR exposure for anticancer immunosurveillance and enhanced anti-tumor effect of C + D treatment." (PMID 39090653, 2024). "One study reveals that in a prophylactic tumor vaccination model using PDT-treated TC1 lung cancer cells, redaporfin acts as an ICD inducer that can trigger eIF2a phosphorylation, DAMPs release and inhibit tumor growth." (PMID 36619616, 2022). "The PERK/eIF2a signalling pathway was positively regulated by UTP14A, and its tumour-promoting effect was further activated by overexpression of UTP14A." (PMID 33391409, 2021). "Western blot analyses and immunohistochemistry of the harvested tumor tissues also revealed that (S)-crizotinib treatment increased the levels of ATF4, CHOP, p-eIF2a indicating activation of the ER stress pathway." (PMID 28882182, 2017). "Punctate staining of p-GCN2 and p-eIF2a and 4E-4EBP1 interaction in xenografts also supports transient and localized GCN2-eIF2a regulation with dynamic translation control during tumor evolution." (PMID 33135632, 2020). "In addition, oral administration of 6-Shogao suppressed the pro-survival pathway of p-PERK, eIF2a and p-eIF2α while it increased the cleavage of caspase-3, leading to reduction in SMMC-7721 tumor xenografts model." (PMID 30081573, 2018). "Interestingly, they found that during tumor initiation, the translational apparatus is redirected towards unconventional upstream initiation sites, in particular, involving CUG codons, and that eIF2A is essential for enhancing the translational efficiency from these sites." (PMID 32192132, 2020).